NR3C1 (nuclear receptor subfamily 3 group C member 1)
Diseases named in the same sentence as NR3C1 in open-access papers (continued):
Sharing a sentence is not in itself a finding about the gene and the disease.
epilepsy (6 papers, 2013 to 2025). A brain disorder characterized by episodes of abnormally increased neuronal discharge resulting in transient episodes of sensory or motor neurological dysfunction, or psychic dysfunction. "This study investigated the relationship between drug response to epilepsy treatment and the rs41423247 polymorphism on the NR3C1 gene or the SNP rs324420 on the FAAH gene." (PMID 39920787, 2025). "Sequencing of target gene loci in 105 epilepsy patients showed that 8 cases of NR3C1 rs41423247 were wild type (CC) and 97 cases had gene mutations, including 32 cases of heterozygous mutations (CG) and pure 65 cases of combined mutation (GG)." (PMID 39920787, 2025). "Some studies have suggested that polymorphisms in the NR3C1 gene may indirectly affect the metabolism and transport of epilepsy drugs by affecting the function of the hypothalamic–pituitary–adrenal axis (HPA)." (PMID 39920787, 2025). "In addition, the polymorphism of NR3C1 gene may affect the metabolism and transport of epilepsy drugs." (PMID 39920787, 2025). "The polymorphism of NR3C1 rs41423247 might influence the drug response of epilepsy children." (PMID 39920787, 2025). "In the clinical treatment of patients with epilepsy, understanding the genotype of the NR3C1 rs41423247 site can help doctors develop a more personalized treatment plan." (PMID 39920787, 2025). "NR3C1 rs41423247 and FAAH rs324420 polymorphisms were detected by the polymerase chain reaction in 105 pediatric epilepsy patients." (PMID 39920787, 2025). "Therefore, the role of NR3C1-mediated immune response in epilepsy drug response is worth exploring in depth." (PMID 39920787, 2025). "Then explore the personalized epilepsy treatment strategy based on NR3C1 and FAAH." (PMID 39920787, 2025). "Therefore, in the future, large-scale clinical studies can be conducted to collect NR3C1 and FAAH gene information and epilepsy drug treatment response data, and analyze the relationship between NR3C1 and FAAH gene polymorphisms and epilepsy drug response." (PMID 39920787, 2025). "The functional status of the glucocorticoid receptor encoded by the NR3C1 gene may affect the regulatory effect of glucocorticoids on the nervous system, and thus affect the efficacy of epilepsy drugs." (PMID 39920787, 2025). "Thus, future studies should take into account external factors and observe the relationship between NR3C1 and FAAH genetic polymorphisms and epilepsy drug response after controlling for these factors." (PMID 39920787, 2025). "Furthermore, the hub genes of AD- and epilepsy-associated GCMs were captured by weighted key driver analysis (wKDA), including TRPC1, C2ORF40, NR3C1, KIAA0368, MMT00043109, STEAP1, MSX1, KL, and CLIC6." (PMID 34697589, 2021). "Furthermore, the hub genes of each AD- and epilepsy-associated GCM were captured, including TRPC1, C2ORF40, NR3C1, KIAA0368, MMT00043109, STEAP1, MSX1, KL, and CLIC6." (PMID 34697589, 2021). "Therefore, it is proposed that the GR-encoding gene NR3C1 may participate in the pathogenesis of epilepsy by regulating BDNF, and NR3C1 is a possible shared gene for AD and epilepsy." (PMID 34697589, 2021). "Nowadays, the SNPs in NR3C1 and FAAH on the drug response of epilepsy remain unclear." (PMID 39920787, 2025).
mental disorder (6 papers, 2019 to 2025). A disease that has its basis in the disruption of mental process. "Other studies in human pathology have also associated NR3C1 methylation to mental disorders, lifestyle, and behavioral factors." (PMID 40490135, 2025). "Besides hormonal receptors and microRNAs, several genes that are differentially methylated in both sexes in the same CGs when Nr3c1 is deficient are also associated with neuronal and mental disorders (6 out of 17 CGs)." (PMID 30655507, 2019). "Additionally, prior studies have reported links between NR3C1 methylation and mental disorders." (PMID 40558833, 2025). "The research progress of NR3C1, FKBP5, BDNF, KITLG and other genes will provide a solid theoretical basis for the improvement of mental disorders in children after trauma." (PMID 36458128, 2022).
Parkinson disease (6 papers, 2009 to 2024). A progressive degenerative disorder of the central nervous system characterized by loss of dopamine producing neurons in the substantia nigra and the presence of Lewy bodies in the substantia nigra and locus coeruleus. "Among the few genes which continued steady rise in placental expression until term, NR3C1 coding for glucocorticoid receptor has been implicated in rheumatism and the malfunction of NRCAM and NEDD9 is related to brain disorders such as autism, Alzheimer’s and Parkinson’s disease." (PMID 23145134, 2012).
pituitary adenomas (6 papers, 2017 to 2026). "Among others, somatic mutations altering the NR3C1 genetic locus have rarely been reported in ACTH-secreting pituitary adenomas." (PMID 35742910, 2022). "It is worth mentioning that the genetic analysis of the pituitary adenoma also revealed a frameshift deletion of the nuclear receptor subfamily 3 group C member 1 (NR3C1) gene that encodes for the glucocorticoid receptor." (PMID 34489873, 2021). "Exome sequencing excluded a causative germline mutation but showed somatic mutations of the β-catenin protein gene (CTNNB1) in the adrenal adenoma, and of both the ubiquitin specific peptidase 8 (USP8) and the glucocorticoid receptor (NR3C1) genes in the pituitary adenoma." (PMID 34489873, 2021). "Later studies based on next generation sequencing (NGS) reported a prevalence of somatic mutations of NR3C1 around 6% of cases studied so far, suggesting they may not be rare events in ACTH-secreting pituitary adenomas." (PMID 35742910, 2022).
Autoimmunity (5 papers, 2012 to 2021). The occurrence of an immune reaction against the organism's own cells or tissues. "Glucocorticoid receptor gene (NR3C1) single nucleotide polymorphisms (SNPs) are implicated in differences in predisposition to autoimmunity and steroid sensitivity." (PMID 34831409, 2021). "Thus, FKBP4 and NR3C1 could serve as notable therapeutic molecules against NRF2-dependent tumorigenesis, autoinflammation, and autoimmunity in the future." (PMID 35087512, 2021).
central obesity (5 papers, 2006 to 2025). "Furthermore, Nr3c1 is significantly associated with abdominal obesity." (PMID 38931172, 2024).
colitis (5 papers, 2015 to 2025). Inflammation of the colon. "Mice with colitis showed altered stress-associated behaviour, which is associated with colitis-induced alterations of Npy, Npy1r, Crh, Crhr1, Bdnf and Nr3c1 gene expression in distinct regions of the brain." (PMID 26066467, 2015). "Building on this, we analyzed the impact of this restored ISC function by Nr3c1 deletion on the stress-aggravated colitis." (PMID 40360481, 2025). "It should be noted that Nr3c1 deletion only partially ameliorates DSS-induced colitis, indicating the existence of other mechanisms connecting stress to intestinal inflammation." (PMID 40360481, 2025). "Importantly, restoration of ISC function by Nr3c1 deletion significantly mitigates this aggravated effect, suggesting a critical role for ISC dysfunction in the stress-increased susceptibility to developing colitis." (PMID 40360481, 2025). "The results showed that while ISC-specific Nr3c1 deletion itself did not affect the severity of DSS-induced colitis, it significantly alleviated the aggravation of colitis severity caused by CRS." (PMID 40360481, 2025). "Hippocampal and amygdalar Nr3c1 expression itself was also decreased by DSS treatment, an effect that may likewise be related to the elevated corticosterone concentrations in colitis." (PMID 26066467, 2015). "Collectively, although not a complete restoration, ISC-specific Nr3c1 deletion significantly protected mice from the stress-driven exacerbation of DSS-induced colitis, suggesting that ISC dysfunction is one of major contributors to the worsening of colitis under chronic stress conditions." (PMID 40360481, 2025).
coronary artery disease (5 papers, 2013 to 2025). "In aorta, we identified perturbations in a number of TFs involved in circadian clock regulation (CRY1, CRY2, PER2), vascular inflammation (PPARG, NR3C1), and those linked in coronary artery disease, including the estrogen receptor, ESR2." (PMID 39896461, 2025).
corticotroph adenomas (5 papers, 2017 to 2022). "Our analysis of the expression level of NR3C1 in corticotroph adenomas showed that tumors causing CD have lower gene expression and accordingly they exhibit higher levels of hsa-miR-124-3p." (PMID 35270010, 2022). "Additionally, whole exome sequencing (WES) analysis revealed several other mutations associated with ACTHomas, including those in the NR3C1, DAXX, ATRX, and HCFC1 genes." (PMID 33266265, 2020). "Silibinin, a C-terminal HSP90 inhibitor, increased the transcriptional activity of NR3C1 in murine corticotroph cells and enhanced the suppression of ACTH secretion in primary corticotroph adenoma cell cultures, restoring glucocorticoid sensitivityin vitro." (PMID 28529722, 2017). "The finding that glucocorticoids modulate NR3C1, CRH-R1, and POMC gene expression in a different fashion suggests that these effectors play a major role in corticotrope adenomas." (PMID 27220856, 2017). "We determined the expression levels of NR3C1 and NR3C2 in corticotroph adenomas with qRT-PCR." (PMID 35270010, 2022). "A single patient with a de novo missense germline NR3C1 mutation associated with an ACTH-PA has also been described, while a child with corticotroph adenoma and partial glucocorticoid resistance had no detectable NR3C1 mutation." (PMID 32201880, 2020).
endometrial cancer (5 papers, 2020 to 2025). Primary or metastatic malignant neoplasm involving the endometrium (mucous membrane that lines the endometrial cavity). "In human HEC-1-A endometrial cancer cells, stable transfection with KLF9 caused the induction of the NR3C1 gene (Glucocorticoid Receptor, GR), suggesting the cross-regulation of KLF9 and GR." (PMID 38067370, 2023). "Compared to normal endometrial cell lines, the mRNA expression of NR3C1 was dramatically lowered in endometrial cancer cell lines, whereas the mRNA expression of PKM2 and ENC1 was significantly upregulated." (PMID 36531950, 2022). "Immunohistochemical analysis based on The Human Protein Atlas database enumerated a significant upregulation of PSMC4, NR3C1, SBDS, and CBLC in endometrial cancer tissues, relative to normal tissues." (PMID 33292199, 2020).
glaucoma (5 papers, 2010 to 2025). Increased pressure in the eyeball due to obstruction of the outflow of aqueous humor. "Additionally, PPI network analysis showed that IRF1, IFI30, NR3C1 and LRRC14 have relatively abundant interacting proteins, suggesting that these genes might act as key regulatory nodes in the molecular pathways underlying HBP and glaucoma." (PMID 41170525, 2025). "The number of interacting proteins for IRF1, IFI30, NR3C1 and LRRC14 was relatively abundant, suggesting that they may play a key role in the regulatory pathways of HBP and glaucoma." (PMID 41170525, 2025).
inflammatory bowel disease (5 papers, 2015 to 2024). A spectrum of small and large bowel inflammatory diseases of unknown etiology. "Further, we found known associations between KLF6, NR3C1, XBP1 and HSF1 with inflammatory bowel disease further validating our analyses." (PMID 30184180, 2018).
osteoarthritis (5 papers, 2019 to 2025). A noninflammatory degenerative joint disease occurring chiefly in older persons, characterized by degeneration of the articular cartilage, hypertrophy of bone at the margins and changes in the synovial membrane. "Agonists of the glucocorticoid receptor, the gene product of NR3C1, a member of both the circadian clock and glial cell pathways, are approved for osteoarthritis pain relief, due to its anti-inflammatory ability." (PMID 40205036, 2025). "Within tier 1, ten candidates have previously been studied in clinical trials of efficacy or in cohort studies of osteoarthritis (six arising from new signals: PPARD, NR3C1, VDR, MAPK14, IGF1R, and CHST3)." (PMID 34450027, 2021).
postnatal depression (5 papers, 2015 to 2021). "Postnatal depression was associated with NR3C1 methylation and anxious-depressed symptoms in daughters of mothers with low prenatal depression (prenatal-postnatal depression interaction for methylation, p < 0.001; for child symptoms, p = 0.011)." (PMID 31438539, 2019). "In a prior study, mood worsening in mothers following delivery (i.e., low prenatal depression followed by high postnatal depression) was associated with methylation of NR3C1 in their offspring, an effect that was reversed by early postnatal maternal stroking of the infant." (PMID 34663459, 2021). "The interaction between prenatal and postnatal depression arose because the association between maternal depression measured at four postnatal time points and NR3C1 1-F promoter methylation was stronger in infants who had been exposed to low levels of maternal depression in utero." (PMID 25942041, 2015). "We, therefore, examined whether each of pre- or postnatal depression have effects on infant NR3C1 1-F promoter DNA methylation at CpG unit 22 and 23, or that they interact to give distinct outcomes." (PMID 25942041, 2015).
psoriasis (5 papers, 2022 to 2025). An autoimmune condition characterized by red, well-delineated plaques with silvery scales that are usually on the extensor surfaces and scalp. "Besides, our PPI network showed that HSPA1A has a significant correlation with NR3C1, a known target of psoriasis." (PMID 39883516, 2024).
psychosis (5 papers, 2020 to 2022). "We investigated methylation levels of DRD2 and NR3C1 in peripheral blood of patients with recent-onset (RO) psychosis using bisulfite pyrosequencing as well as its association with childhood trauma and rumination." (PMID 35968502, 2022). "Dopamine receptor D2 gene (DRD2) and glucocorticoid receptor gene (NR3C1) are implicated in the development of psychosis." (PMID 35968502, 2022). "The present study examined methylation rates of DRD2 and NR3C1 in patients with recent-onset (RO) psychosis using bisulfite pyrosequencing as well as its association with childhood trauma and rumination." (PMID 35968502, 2022). "Second, to strengthen the validity of NR3C1 mRNA’s association with psychosis, we performed a Mendelian randomization analysis." (PMID 32754072, 2020). "NR3C1 expression was significantly associated with a higher risk of conversion to psychosis (OR = 2.03, p = 0.03), independently of any other factor." (PMID 32754072, 2020). "iii) Finally, would such an eQTL be associated with psychosis, thus confirming the environmentally unbiased effect of NR3C1 on risk of psychosis?" (PMID 32754072, 2020). "First, we showed that after adjusting for cortisol levels, an increase in NR3C1 expression was significantly associated with a higher risk of conversion to psychosis." (PMID 32754072, 2020). "Epigenetic alterations of NR3C1 are associated with the pathophysiology of psychosis." (PMID 35968502, 2022). "We hypothesized that there might be altered methylation of NR3C1 in psychosis, which in turn is associated with childhood trauma and rumination." (PMID 35968502, 2022). "Notably, two studies have reported an association between NR3C1 methylation and childhood adversity in psychosis." (PMID 35968502, 2022). "Moreover, a recent study observed that an increase in peripheral expression of the NR3C1 gene (encoding a glucocorticoid receptor) was associated with transition to psychosis among CHR individuals." (PMID 34715990, 2022). "In this context, we hypothesized that, in at-risk individuals, NR3C1 peripheral expression may explain some of the risk of psychosis, independently of cortisol levels, and adjusted by sex, age, cannabis and antipsychotic medication intake." (PMID 32754072, 2020). "We investigated DNA methylation rates at two candidate regions (DRD2 and NR3C1) in patients with RO psychosis and healthy controls." (PMID 35968502, 2022). "Higher methylation of the NR3C1 gene was related to worse performance of attention and immediate memory as well as lower level of general functioning in patients with psychosis." (PMID 33284958, 2021). "The level of NR3C1 methylation was significantly lower in first-episode psychosis patients and significantly higher in SCZ-AR patients compared with other subgroups of participants." (PMID 33284958, 2021). "i) At the hormonal and molecular level, are basal cortisol and NR3C1 expression reliable biomarkers of conversion to psychosis?" (PMID 32754072, 2020). "This suggests that different CpG loci of NR3C1 may participate in psychosis through different regulatory mechanisms." (PMID 35968502, 2022). "Although the functional significance of this difference in methylation is unclear, it suggests that epigenetic aberrations of NR3C1 are associated with the presence of RO psychosis and negative symptoms." (PMID 35968502, 2022). "However, previous studies have provided mixed findings on the role of epigenetic regulation of the NR3C1 in the pathophysiology of psychotic disorders." (PMID 33284958, 2021). "In summary, results of this study indicate that patients with schizophrenia-spectrum disorders show altered levels of NR3C1 methylation that are significantly lower at early stages after the onset of psychosis and significantly higher after subsequent illness exacerbations." (PMID 33284958, 2021).
psychosis (continued). "For NR3C1, results have varied depending on which CpG sites or components were analyzed, e.g., hypomethylation at 1D-CpG8 and hypermethylation at 1B-CpG15 and 1F-CpG21 and hypomethylation or hypermethylation at component 2, including 5 CpG sites, depending on the stage of psychosis." (PMID 35968502, 2022). "In turn, a history of ACEs might be associated with lower NR3C1 methylation, and this observation is not specific to patients with psychosis." (PMID 33284958, 2021). "Increase in the level of NR3C1 methylation and its negative correlation with cognition in patients with psychosis from our sample might be one of the mechanisms underlying this observation." (PMID 33284958, 2021). "Interestingly, higher expression of the NR3C1 gene has been observed in at-risk individuals converting to overt psychosis compared with non-converters." (PMID 33284958, 2021). "As cortisol levels were neither correlated with NR3C1 expression, this may suggest cortisol’s effects in psychosis might be conditional to the underlying biological and genetic background." (PMID 32754072, 2020). "Moreover, NR3C1 expression could be of interest in psychosis, not only through its relationship with cortisol, but also as a possible direct marker." (PMID 32754072, 2020). "We identified aberrant DNA methylation rates in patients with RO psychosis compared to healthy controls at several CpG sites of the NR3C1 exon 1F region but not at the target regions of DRD2." (PMID 35968502, 2022). "The association between a history of adverse childhood experiences and lower NR3C1 methylation is not specific to patients with psychosis." (PMID 33284958, 2021). "However, methylation of the NR3C1 gene at various stages of psychosis has not been investigated so far." (PMID 33284958, 2021). "Our study also demonstrated that methylation of the NR3C1 gene might be related to worse performance of attention and immediate memory as well as lower general functioning in patients with psychosis but not in other groups of participants." (PMID 33284958, 2021). "However, there is not, to our knowledge, any NR3C1 gene expression (mRNA or protein) study in the context of emergence of psychosis." (PMID 32754072, 2020). "Considering that patients with psychotic disorder not otherwise specified, equivalent to OSSO, show different clinical characteristics and better outcome compared to SZ, a separate study on NR3C1 methylation in OSSO is warranted." (PMID 35968502, 2022).